FKBP15 (FKBP prolyl isomerase family member 15)
Description:
May be involved in the cytoskeletal organization of neuronal growth cones. Seems to be inactive as a PPIase (By similarity). Involved in the transport of early endosomes at the level of transition between microfilament-based and microtubule-based movement.
Synonyms: WAFL; KIAA0674; PPP1R76; FKBP133
Tractability: Small molecule: it belongs to a druggable protein family. PROTAC: ubiquitination databases record sites on it; its protein half-life has been measured.
Safety:
Unwanted effects reported when the protein is acted on. In parentheses: how it was acted on, where the effect was seen, and who reports it.
drug toxicity (source: ClinPGx)
overall survival (source: ClinPGx)
thrombocytopenia (source: ClinPGx)
thrombocytopenia and overall survival (source: ClinPGx)
Gene: Protein-coding gene on chromosome 9 (113,161,006 to 113,221,458, reverse strand). Ensembl gene ENSG00000119321.
Subcellular location: Cytoplasm; Cell projection, axon; Early endosome
Subcellular location (Human Protein Atlas): Nucleoli; Cytosol
Gene Ontology:
Molecular function: protein binding; peptidyl-prolyl cis-trans isomerase activity
Cellular component: membrane; growth cone; actin cytoskeleton; axon; cytoplasm; early endosome; endosome
Genetic constraint (gnomAD): Loss-of-function variants: 88 observed, 127.66 expected, observed/expected ratio (o/e) 0.69, 90% interval 0.58 to 0.82. The upper end of that interval is the gene's LOEUF score, 0.82, which puts it in group 3 of 6, group 1 being the genes least tolerant of losing a copy. Missense variants: 1,221 observed, 1,396.4 expected, observed/expected ratio (o/e) 0.87, 90% interval 0.83 to 0.92. Synonymous variants: 525 observed, 526.86 expected, observed/expected ratio (o/e) 1, 90% interval 0.93 to 1.07.
Homologues: Orthologues: macaque FKBP15 (93% identical), chimpanzee FKBP15 (93% identical), dog FKBP15 (83% identical), rabbit FKBP15 (81% identical), pig FKBP15 (81% identical), mouse Fkbp15 (80% identical), rat Fkbp15 (79% identical), guinea pig Fkbp15 (47% identical), zebrafish fkbp15b (44% identical), tropical clawed frog fkbp15 (42% identical), zebrafish fkbp15a (29% identical), Caenorhabditis elegans fkb-5 (4% identical), and 1 more. Paralogues in human: FKBP4 (7% identical), FKBP5 (7% identical), FKBP9 (7% identical), FKBP10 (6% identical), FKBP8 (6% identical), FKBP6 (5% identical), FKBP3 (5% identical), FKBP14 (4% identical), FKBP7 (4% identical), FKBPL (4% identical), FKBP11 (4% identical), FKBP2 (3% identical), and 6 more.
Diseases named in the same sentence as FKBP15 in open-access papers:
FKBP15 is named in the same sentence as 3 diseases in open-access papers, as found by Europe PMC text mining. Sharing a sentence is not in itself a finding about the gene and the disease. The quoted sentences say what the papers report.
ulcerative colitis (1 paper, 2017). An inflammatory bowel disease involving the mucosal surface of the large intestine and rectum. "Sequence homology analyses suggest that R148.3 is an ortholog of the human FK506 binding protein 15 (FKBP15) gene, recently implicated in ulcerative colitis." (PMID 28620088, 2017).
FKBP15 also shares sentences with these, for which no sentence is quoted: infection (1 paper); megalencephalic leukoencephalopathy (1).